INS (insulin)
Diseases named in the same sentence as INS in open-access papers (continued):
Sharing a sentence is not in itself a finding about the gene and the disease.
diabetes (continued). "The American Diabetes Association established a working group on the issue of insulin pricing, and in 2018, the working group published its findings, including the need for more available biosimilar insulins." (PMID 34636912, 2021). "Patients with diabetes have underlying disruptions in carbohydrate and lipid metabolism that present as elevated blood glucose levels due to impaired insulin sensitivity or production." (PMID 33466750, 2021). "Diabetes Mellitus is a complex and multi factorial disease which is caused either by insufficient production of insulin or insulin resistance by the cells or both." (PMID 34321097, 2021). "Particularly, type 2 diabetes is the main type of diabetes, which is mainly caused by glucose metabolism disturbances and the increase in blood glucose concentration due to the loss of insulin production by pancreatic β cells." (PMID 34361791, 2021). "ATP5MD, also named USMG5 (upregulated during skeletal muscle growth protein 5), encodes the ATP synthase membrane subunit and also known as diabetes mellitus–associated protein in insulin sensitive tissues, or DAPIT36." (PMID 34021155, 2021). "Resistance to the hormones insulin and leptin in the offspring affects the metabolic milieu predisposing the individual to obesity and diabetes." (PMID 34796053, 2021). "Intensive-insulin treatment (IIT) strategy for patients with type 1 diabetes mellitus (T1DM) has been associated with sedentary behaviour and the development of insulin resistance." (PMID 34229671, 2021). "Diabetes is caused by insufficient insulin secretion due to β-cell loss, or a pancreatic dysfunction." (PMID 33996792, 2021). "Diabetes is a chronic metabolic disorder caused by various pathological mechanisms such as insulin resistance or insufficient insulin secretion, resulting in increased concentrations of glucose in the blood." (PMID 34071638, 2021). "Using the DCP scale highlights worsening QOL and is associated with higher glycaemic levels and the use of insulin or tablets if the patient is having a larger number of complications due to diabetes." (PMID 34501838, 2021). "Ages 41–70 years, males, longer diabetes duration, hyperglycaemia and hypertension, insulin users and lower socio-economic status were associated with both DR outcomes." (PMID 34945199, 2021). "Diabetes is a group of chronic metabolic diseases resulted from insulin secretion and (or) action deficiency." (PMID 35002992, 2021). "Defects in insulin signalling is the primary cause for diabetes, obesity and various metabolic disorders." (PMID 33606785, 2021). "It was reported that ginsenoside Re had the effects of hypoglycemic, hypolipidemic, anti-oxidant stress, improving insulin resistance, increasing insulin level, and attenuating diabetes-associated cognitive decline." (PMID 34771066, 2021). "The pro-inflammatory cytokine TNF-α was involved in the pathogenesis of diabetes by causing an increase in insulin resistance and a significant elevation in insulin levels in the diabetic microenvironment." (PMID 34975496, 2021). "Most probably, the simple administration of an antioxidant such as crocin cannot compensate for the serious weight loss caused by diabetes, at least when insulin levels remain compromised." (PMID 32161725, 2020). "In the sulfonylurea/insulin group, relative risk reductions persisted at 10 years for any diabetes-related endpoint (9%, p = 0.04) and for microvascular disease (24%, p = 0.001)." (PMID 32489427, 2020). "The CPP extract has also ameliorated diabetes-induced pancreatic β cells loss by repairing the antioxidant defense mechanism and restoring insulin, amylin, leptin, and carbohydrate-metabolizing enzyme levels." (PMID 32256963, 2020). "Insulin resistance is commonly associated with T2DM, as this type of diabetes mellitus arises from impaired insulin action, thus impeding insulin signaling." (PMID 32842567, 2020).
diabetes (continued). "Mutations in HNF1A lead to decreased insulin secretion, and progressive damage of beta cells and thus cause the onset of diabetes." (PMID 31754975, 2020). "In group A diabetic CHC population, high fasting blood glucose levels with normal serum insulin levels was an important observation assuming that HCV in group A caused diabetes by some other etiological factor." (PMID 33520544, 2020). "Our findings are of broad significance because β-cell failure induced by combination of β-cell loss and impaired insulin secretion from remaining β-cells is a key pathologic basis for diabetes." (PMID 31980627, 2020). "Type 1 diabetes mellitus (T1DM), a disorder caused by an autoimmune response against insulin-producing β cells in the pancreatic islets, is the most severe form of diabetes mellitus." (PMID 33183315, 2020). "Lower post-prandial glucose (PPG) and insulin (PPI) responses to foods are associated with reduced diabetes risk and progression." (PMID 32647531, 2020). "The occurrence of GAD65Ab constitutes an essential decision criterion for diabetes management, predicts the rate of C‐peptide loss and the need for insulin treatment." (PMID 32378803, 2020). "It is also well established that the raised oxidative stress is associated with increasing the risk factors of diabetes such as altering pancreatic insulin secretion and the effects of the hormone on target cells." (PMID 33178838, 2020). "Overall, diabetics are at a greater risk for AD and the brains of individuals with AD have higher levels of insulin, insulin receptor, and insulin signaling." (PMID 33192310, 2020). "As the primary outcome, the number of hypoglycemic episodes per 24 h of CGM, suggests, this pilot study focused on the hypoglycemic burden in insulin-treated diabetes patients of any causality." (PMID 33292431, 2020). "An absolute or relative deficiency of functional insulin producing β cells is the pathological feature of both types of diabetes." (PMID 32613468, 2020). "Diabetes is a group of metabolic diseases, mainly caused by defects in insulin secretion, insulin activity, or both." (PMID 33343355, 2020). "Thiazolidinediones (rosiglitazone, pioglitazone) are oral insulin-sensitizing medications used in type 2 diabetes mellitus that can reduce glucose with a minimal risk of hypoglycemia and potential anti-atherosclerotic effects." (PMID 33324553, 2020). "Rad 35-kDa (Ras Associated with Diabetes) Ras-guanosine triphospha-tase (GTPase) is positively expressed in response to insulin." (PMID 32823525, 2020). "In case of diabetes and diabetes-associated dysfunctions, effective delivery of insulin via oral route by these nanoformulations is highly preferred compared to the available parenteral preparations, due to a higher patient compliance." (PMID 32478050, 2020). "Insulin controls hyperglycemia caused by diabetes, and virtually all treatments require exogenous insulin." (PMID 31918694, 2020). "Meanwhile, vitamin D deficiency or insufficiency is involved in the regulation of insulin secretion, glucose levels, and inflammation causing adipose metabolic diseases, such as obesity, multiple sclerosis, diabetes, and fatty liver." (PMID 32149047, 2020). "Type 1 diabetes mellitus is a chronic condition characterized by an absolute insulin deficiency and a lifelong dependency on exogenous insulin." (PMID 32184823, 2020). "Previous studies have indicated that acyl chain length and saturation of TAGs in the plasma are associated with risk for diabetes as well as improvements in insulin sensitivity after diet-induced weight loss." (PMID 32880685, 2020). "Diabetes mellitus is one of the risk factors for the pathogenesis of AD by impairment of insulin signaling and glucose metabolism, both centrally and peripherally." (PMID 32503113, 2020). "Diabetes mellitus (DM) is a group of metabolic disorders characterized by decreased insulin secretion, insulin resistance, or both, causing a hyperglycemic state." (PMID 32656036, 2020).
diabetes (continued). "These differentiated cells produced human insulin, decreased blood glucose levels and minimized diabetes-associated complications such as weight loss, dehydration, cataracts, delayed wound healing and sedative behavior in a mouse model of diabetes mellitus." (PMID 32742977, 2020). "Diabetes mellitus (DM) is caused either by deficiency of insulin (T1DM) or by downregulation of receptors for insulin (T2DM)." (PMID 33266387, 2020). "Diabetes mellitus is a metabolic health disease, characterised by elevated blood sugar levels due to genetics, acquired deficiency, or malfunction of insulin." (PMID 32183393, 2020). "Upon revisiting clinical data on these two allele carriers, it was found that one of the carriers with insulin-treated diabetes from age 14 years was positive for GAD and IA2 autoantibodies." (PMID 32910913, 2020). "To examine potential mechanisms through which statins mediated DNA methylation at cg06500161 that led to increased risk of diabetes, we separately correlated gene expression levels with statin use, cg06500161 methylation and fasting glucose and insulin levels." (PMID 32612641, 2020). "This together with the reduced expression of β-cell maturity genes suggest that stress-induced diabetes development in the IKK2-DNPdx1 model is accompanied by the loss of β-cell identity as evidenced by loss of insulin expression." (PMID 31682591, 2020). "Type 1 diabetes mellitus (T1DM) is an autoimmune disease caused by dysfunction of the beta cells of the pancreas which results in an almost absolute deficiency of insulin." (PMID 32280715, 2020). "At the beginning of pregnancy, we found that maternal birth in sub-Saharan Africa, preexisting insulin-treated diabetes, nulliparity and mode of conception were risk factors for severe acute maternal morbidity." (PMID 32109258, 2020). "PrxIV is another subtype implicated in its protective role against diabetes due to stimulation of enhanced insulin secretion." (PMID 32903449, 2020). "As anticipated, we also observed differences in the association of insulin sensitivity with beta cell function between the prediabetes and the diabetes cohorts." (PMID 32002573, 2020). "It is well known that diabetes causes body weight loss because of the loss of availability of glucose as energy, resulting from insulin tolerance or decrease of insulin secretion." (PMID 32678222, 2020). "Diabetes mellitus (DM), a frequent life-threatening metabolic disorder worldwide, is characterized by hyperglycemia caused by either insulin resistance or declined insulin secretion." (PMID 32280378, 2020). "Trials of analog insulin have consistently shown a reduced risk of hypoglycaemia compared with human insulin, and it is now standard‐of‐care for T1D diabetes treatment in high‐resource nations." (PMID 32704558, 2020). "Data from primary cultured rat hepatocytes demonstrated that insulin decreased the expression of CYP2E1 and CYP2B protein and mRNA, inferring that a deficiency of insulin is also a reason that diabetes induces the expression of CYP2El and CYP2B." (PMID 32290519, 2020). "Dysregulations in insulin and glucose metabolism, the pathophysiological underpinnings of diabetes mellitus, are associated with an increased risk of cardiovascular disease due to the accelerated accumulation of atherosclerosis." (PMID 31958313, 2020). "Diabetes mellitus (DM), affecting millions of people worldwide, is a metabolic disease caused by the loss or impaired function of insulin-producing pancreatic β cells." (PMID 33121533, 2020). "Diabetes mellitus is mainly caused by genetic, environmental influence, microbial infection, immune system dysfunction, and mental factors that result in insufficient insulin secretion and insulin resistance." (PMID 32850735, 2020).
diabetes (continued). "A systematic review showed that prepregnancy BMI, family history of diabetes, advanced maternal age, increased HbA1c levels, and increased insulin use during pregnancy were associated with the future development of T2DM in GDM patients." (PMID 32377519, 2020). "This is compatible with the severe insulin deficiency that results in a presentation of diabetes soon after birth existing in utero, resulting in reduced insulin-mediated growth and hence lower birthweight." (PMID 33029656, 2020). "In a case-control study of diabetic AA subjects, duration of diabetes, systolic hypertension and insulin use were found to be risk factors for the development of PDR." (PMID 32682412, 2020). "Diabetes mellitus (DM) is defined as a metabolic disease that causes hyperglycemia due to alterations in the release and/or function of insulin." (PMID 32520205, 2020). "The findings revealed that several constituents of Viola odorata such as rutin, eugenol, vanillic acid, stigmasterol, and limonene have an association with insulin activity, which suggests that Viola odorata has the potential to manage diabetes." (PMID 33490239, 2020). "SERCA2 heterozygous mice show impaired cytosolic Ca2+, impaired insulin secretion and susceptibility to diet-induced diabetes." (PMID 32042314, 2020). "In other words, the interaction between autophagy and energy homeostasis amplifies the adverse effects of decreased insulin signal transduction caused by insulin deficiency or resistance in the hearts of individuals with diabetes." (PMID 33328993, 2020). "Flavan-3-ols from cocoa have been found to be associated with a reduced risk of stroke, myocardial infarction, and diabetes, as well as improvements in lipids, endothelial-dependent blood flow and blood pressure, insulin resistance, and systemic inflammation." (PMID 32781724, 2020). "These mice develop insulin-deficient diabetes at young age because of β-cell stress, reminiscent of human type 1 diabetes (T1D)." (PMID 32726619, 2020). "There is some biological plausibility for a beneficial effect of sports on dementia risk, linked to positive effects on insulin and C-peptide metabolism, as recently demonstrated in subjects with a family history of diabetes." (PMID 33138082, 2020). "Type 1 DM, also referred to as juvenile diabetes or insulin-dependent diabetes mellitus, is caused by the pancreas’s failure to produce enough insulin." (PMID 32575461, 2020). "This scenario forecasted the impact of more children entering adulthood at a higher weight status on insulin sensitivity, placing them at risk of early development of diabetes mellitus." (PMID 32475837, 2020). "Serum levels of lutein and β-carotene were found to be significantly negatively associated with diabetes-related markers (blood insulin, HOMA-IR) in both sexes, and they were also found to be negatively associated with FBG in females." (PMID 32752047, 2020). "Among the potential factors related to the risk of progression to T1D, the positivity of multiple autoantibodies is demonstrated to be a major risk factor of developing insulin-requiring diabetes." (PMID 32670194, 2020). "It is biologically plausible that physical activity is correlated with lower diabetes risk since it reduces insulin-mediated and non–insulin-mediated glucose disposal." (PMID 33113802, 2020). "Previously, SCGN was associated with beta-cell proliferation, insulin secretion and was increased in patients with diabetes mellitus." (PMID 32708966, 2020). "Type 1 diabetes mellitus (T1DM) affects 10-15% of patients with diabetes mellitus (DM) and is caused by autoimmune destruction of pancreatic beta-cells, making patients dependent of insulin for life." (PMID 32236312, 2020). "Other, less common types of diabetes are as follows: those associated with genetic defects of beta cells or insulin action, drug and chemical-induced diabetes, endocrinopathies, and disease of the exocrine pancreas (type 3c diabetes)." (PMID 32742851, 2020).
diabetes (continued). "In diabetes, together with hyperglycemia caused by a deficiency or insensitivity to endogenous insulin, a disorder in carbohydrate metabolism is also present." (PMID 32927638, 2020). "The prediabetic individual’s final progression to overt diabetes is synonymous with a decline in insulin secretion and is accompanied by the loss of functional β-cell mass." (PMID 33379327, 2020). "Diabetes mellitus (DM) is a chronic disease characterized by insulin deficiency and/or insulin insensitivity which leads to chronic hyperglycemia and disturbance of carbohydrate, lipid, and protein metabolism." (PMID 32717985, 2020). "Diabetes mellitus (DM), as defined by the American Diabetes Association (2010), refers to a group of metabolic disorders primarily induced by impaired insulin secretion and/or action." (PMID 32974105, 2020). "fIGF-1 concentrations are linked with the occurrence of diabetes in women with insulin concentrations beyond the median, but below median IGFBP-1 concentrations." (PMID 33905470, 2020). "Elevated blood glucose is a pathological feature of diabetes mellitus associated with an inadequate control of the sugar by insulin." (PMID 32183843, 2020). "Diabetes is a chronic, metabolic disease, which is commonly associated with increased blood glucose levels caused by impaired secretion or function of insulin." (PMID 33905473, 2020). "Diabetes is a metabolic disorder characterized by chronic hyperglycemia resulting from deficiency of secretion (type I diabetes) and/or insulin action (type II diabetes)." (PMID 33293987, 2020). "Diabetes mellitus (DM) is characterized by deficiency or resistance to insulin in peripheral tissues with persistent hyperglycemia, which resulted in increasing healthcare costs globally." (PMID 32908938, 2020). "Nevertheless, there are two major reasons to cause diabetes: impaired insulin secretion and impaired insulin action." (PMID 32982969, 2020). "Gln has previously been associated with obesity and diabetes as Gln plays a valuable role in gluconeogenesis and insulin secretion." (PMID 33198236, 2020). "In vitro data on metformin suggest a protective effect on bones and that metformin improves bone quality and decreases the risk of fracturs in patients with diabetes, in addition to improving glycemic control and insulin sensitivity." (PMID 32887312, 2020). "Type 1 diabetes mellitus is a result of cellular-mediated autoimmune destruction of the beta cells of the pancreas, causing an absolute deficiency of insulin secretion." (PMID 32855973, 2020). "In animal models, increased Cadm2 expression is associated with obesity, while knockout or loss of Cadm2 prevents obesity, improves insulin sensitivity and protects mice from developing diabetes." (PMID 33424774, 2020). "The functional defect and deficiency of insulin both cause diabetes to develop accompanied by elevated fasting and postprandial glucose levels and elevated free fatty acid levels." (PMID 33905470, 2020). "In vitro and in vivo studies reveal that Kindlin-2 loss dramatically reduces insulin expression and secretion and impairs β-cell proliferation and mass, resulting in severe diabetes-like phenotypes." (PMID 31980627, 2020). "Because of its lower degradation rate and negligible hepatic clearance compared to insulin, C-peptide is a cornerstone for the assessment of non-diabetes-associated hypoglycemia and the diagnosis of conditions including insulinoma and factitious hypoglycemia." (PMID 33301501, 2020). "In a Vietnamese study of people aged 60 years or older with type 2 diabetes, a significant decrease in HRQoL was associated with a longer duration of diabetes, use of insulin, and presence of comorbidity." (PMID 33291678, 2020). "Some studies have shown that loss of muscle strength is associated with diabetes and that insulin resistance causes muscle protein loss." (PMID 33002067, 2020).